CD47 (CD47 molecule)
Diseases named in the same sentence as CD47 in open-access papers (continued):
Sharing a sentence is not in itself a finding about the gene and the disease.
tumor (continued). "CD47 is a ligand expressed in many tumor cell types, and by binding with the macrophage receptor CD47-signal regulatory protein alpha (SIRPα), it can regulate the phagocytic activity of macrophages." (PMID 38730724, 2024). "The activation of YAP signalling pathway prompted CSLC to release cytokines, which further upregulated the expression of CD47, thus effectively inhibiting the phagocytosis of tumour cells." (PMID 39184916, 2024). "IBI322, an anti-CD47/PD-L1 bispecific antibody, is highly selective for tumor cells but mitigates the effects of other cells." (PMID 38464520, 2024). "During the development of tumors, tumor cells transmit a “don’t eat me” signal through the up-regulation of CD47 and its binding to signal regulatory protein α (SIRPα) on the surface of antigen-presenting cells (APCs) via the CD47-SIRPα pathway." (PMID 38324678, 2024). "CD47-targeting bivalent mAbs are known to induce hemolytic anemia due to their on-target off-tumor depletion of RBCs33,34." (PMID 38448430, 2024). "Due to the specific affinity of the RS17 peptide for CD47 on tumor cells and the innate homing ability of the M1 EVs, REV@SR780Fe@LEV-RS17 NPs targeted tumors and accumulated at tumor sites after intravenous administration." (PMID 39033108, 2024). "Anti-tumor therapeutic strategies targeting CD47 have been developed and applied to lung cancer patients for whom chemotherapeutic agents are ineffective and show potent tumor suppression." (PMID 39678502, 2024). "Anti-CD47 monoclonal antibody Hu5F9-G4 can activate the phagocytosis and other killing effects of macrophages on tumor cells." (PMID 39065562, 2024). "At 28 days post tumor inoculation, we found enhanced numbers of macrophages, monocytes and neutrophils in the spleen and tumor, as well as an increased proportion of cDC1 compared to cDC2 populations upon CD47 × PD‐L1 BisAb therapy, as previously reported." (PMID 39584189, 2024). "As a macrophage immune checkpoint, CD47 can interact with Sirpα on macrophages to provide a “don’t eat me” signal, bind to and block Sirp-mediated phagocytosis of tumor cells." (PMID 38832992, 2024). "Lastly, we used FACS and fluorescent conjugated antibodies to quantify CD47 protein on the cell membrane, critical aspect of its immune modulatory function during tumor progression." (PMID 39742254, 2024). "In cancer, however, CD47 is overexpressed on tumor cells, allowing them to evade phagocytosis by the immune system." (PMID 38261139, 2024). "The CD47-SIRPα signaling pathway serves as a key phagocytic checkpoint, with tumor cells often overexpressing CD47 to evade phagocytosis." (PMID 39379603, 2024). "Tumor cells express high levels of CD47 to enable immune evasion from macrophage clearance for survival and spreading." (PMID 38992659, 2024). "Several antibodies have been developed to target CD47, which blocks the activation of SIRPα and reprograms TAMs to engulf tumor cells." (PMID 39516356, 2024). "Nevertheless, recent research has shown that enhancing macrophage-mediated anti-tumor activity requires more than just lowering inhibitory signals like CD47." (PMID 39309874, 2024). "Their skeleton is built of two arms—one blocks the CD47-SIRPα axis and the other binds tumor-specific antigens, thereby increasing the precision of BsAbs." (PMID 38892394, 2024). "CD47 is a signaling molecule that helps tumor cells escape the immune system, and it has been found that blocking CD47 can have a beneficial effect on tumor immunotherapy." (PMID 38564002, 2024). "Simultaneously targeting CD19, naturally occurring on B-cell lineage and CD47, commonly expressed by tumor cells as a means to avoid macrophage phagocytosis, it destroys tumor cells in B-cell lymphoma, reducing the killing of regular B cells." (PMID 38672662, 2024). "IMM01, a recombinant human SIRPα fusion protein, can bind to CD47 on the tumor cell membrane to mediate macrophage phagocytosis of tumor cells." (PMID 38464520, 2024).
tumor (continued). "Our data showed a notable trend linking CD47 expression to tumor grade, while also suggesting an interesting correlation between enhanced abundance of CD47 expression and a reduced hazard risk of disease progression." (PMID 38493445, 2024). "CD47 on the surface of tumor cells can release the signal 'don't eat me' by binding to the SIRPα receptor on the surface of macrophages, helping tumor cells to evade immune killing." (PMID 39513610, 2024). "EVs containing CD47 evade macrophage phagocytosis and induce ferroptosis by delivering drugs to tumor cells." (PMID 38543204, 2024). "(i) Tumor growth at early timepoints where growth is still linear shows suppression of tumors comprised of B16F10 CD47 KO cells pre-opsonized with convalescent sera and anti-Tyrp1, compared to mouse IgG2a isotype controls." (PMID 38805560, 2024). "One example of such therapy is the construction of CAR-Ms that target HER2 and CD47 on the surface of tumor cells." (PMID 38794298, 2024). "For tumor-expressed CD47, tumor delivery strategies would need to be considered given the low BBB penetrance of antibodies." (PMID 38786045, 2024). "miR-340 overexpression can downregulate CD47 and inhibit tumor growth via regulating macrophage phagocytosis." (PMID 38383737, 2024). "Immune checkpoint molecules such as PD-L1, CTLA-4, and CD47 were identified as key players in tumor immune evasion, contributing to tumor growth and metastasis." (PMID 39539964, 2024). "Although CPMV showed anti-tumor effects, CD47 Ab appeared to be ineffective in the treatment of C57BL/6 mice by intraperitoneal injection." (PMID 38832992, 2024). "Its selective binding to pyroglutamate cycled CD47 effectively blocks the CD47/SIRPα axis signaling pathway, leading to enhanced phagocytosis of tumor cells by macrophages." (PMID 38429732, 2024). "It has been reported that autophagy in tumour cells can affect macrophage phagocytosis by increasing CD47 expression through autophagy." (PMID 38652105, 2024). "Due to the pH sensitivity of the system, aCD47 can be freed in the acidic tumor microenvironment (TME) to interfere with cancer cells via CD47." (PMID 38560565, 2024). "Several clinical trials have reported that CD47 blockade reduces tumor growth in hematological malignancies." (PMID 38414061, 2024). "Nanoparticles loaded with an anti-CD47 antibody achieved antitumor effects in a 4T1 tumor-bearing mouse model by continuously releasing the antibody to block the CD47-SIRPα axis." (PMID 38464520, 2024). "Antibodies and recombinant SIRPα constructs that block the CD47-SIRPα interaction on macrophages exhibit anti-tumor activities in mouse models and are in ongoing clinical trials for treating several human cancers." (PMID 38495618, 2024). "From the protein expression level, it was again proved that CD47 was highly expressed in tumor tissues, especially on the cell membranes of tumor cells." (PMID 38720108, 2024). "CD47 blockade resulted in elimination of immunosuppressive cells from the tumor microenvironment, consequently favoring an anticancer immune response." (PMID 38892394, 2024). "Blocking SIRPα on the surface of TAMs and DCs, which blocks its interaction with CD47 on the surface of tumor cells and their subsequent “don’t eat me” signal, restores the phagocytosis of tumor cells." (PMID 38433837, 2024). "First, the CD47/SIRPA blockade cannot effectively induce phagocytosis on its own when the cancer cells reside in the tumor mass in which TAMs exist." (PMID 38920727, 2024). "The combination of DCA and neutralizing CD47 antibody produced a more pronounced impairment of tumor growth relative to either agent alone, which translated into further prolongation of survival of tumor-bearing mice." (PMID 39545414, 2024). "Inhibition of the CD47-SIRPα interaction by antibodies has shown increased phagocytosis of tumor cells and reduction of tumor burden across various cancer types." (PMID 38785789, 2024).
tumor (continued). "MYC, CD47 and PD-L1 are considered to generate an immunosuppressive “cold” tumor microenvironment in CRC, providing insight into why LINC00460 induces immune escape and the shaping of suppressive tumor immune microenvironment." (PMID 39135122, 2024). "CD47 blockade has been implemented in various models and clinical trials to enhance phagocytosis, augment T cell infiltration into tumors, and reduce tumor burden both in vitro and in vivo." (PMID 38720108, 2024). "The reasoning for the combination being more potent is a synergism in which anti-GD2 primes tumor cells for phagocytosis via the upregulation of surface proteins, while anti-CD47 prevents the tumor’s “don’t eat me” signals." (PMID 38279265, 2024). "Tumor cells exhibit diverse surface proteins, and the integral membrane protein CD47 is found to be amplified in tumor cells." (PMID 38397971, 2024). "Specifically, we found that CD36 and CD47 were ubiquitously expressed in tumor cells across virtually all types of cancers evaluated in this study." (PMID 39627379, 2024). "Subsequently, CD47/SIRPα axis blockade was shown to effectively promote tumor cell phagocytosis as well as enhanced antigen presentation leading to a strong T cell mediated tumor response." (PMID 38322418, 2024). "For instance, the macrophage phagocytic response in the context of the anti‐tumor effects following the disruption of SIRPα‐CD47 has been investigated utilizing in vitro live microscopy and in vivo bioluminescence access diverse tumor types." (PMID 39387259, 2024). "It has been reported that tumor employs CD47-Sirpα to inactivating macrophage and achieves immune evasion." (PMID 39707436, 2024). "CD47, by binding to its receptor signal regulatory protein-alpha (SIRPα) on anti-tumor macrophages, promotes AML cell survival by blocking macrophage phagocytosis." (PMID 38459166, 2024). "AbCD47 can target and block CD47 on the surface of tumor cells to disable the “Don't eat me” signal." (PMID 38520730, 2024). "The synergistic effect of anthracyclines and CD47 mAb has been observed to enhance tumor ablation in vivo." (PMID 39040441, 2024). "For instance, the use of CD47 blockers can enhance the phagocytosis of M2 TAMs and inhibit tumor advancement in endometrial cancer." (PMID 39169402, 2024). "A recent study showed that tumor cells with low CD47 expression induce delayed phagocytosis resulting in incomplete digestion and subsequent THC formation." (PMID 38611120, 2024). "Previous studies have demonstrated that blocking CD47 significantly enhances CD103+ dendritic cell absorption of tumor DNA, activating the cGAS-STING pathway." (PMID 39379603, 2024). "For example, while anti-GD2 therapy alone lacks significant efficacy, the simultaneous targeting of GD2 and CD47 has shown promise in reducing tumor size." (PMID 38892305, 2024). "Tumor cells upregulate CD47 expression to evade phagocytosis, with CD47 acting as a ligand for three different receptors: signal regulatory protein alpha (SIRPα), thrombospondin-1 (TSP-1), and integrins, including αvβ3 and α2β1." (PMID 38785789, 2024). "The overexpression of MYC induces the expression of CD47 and PD-L1 in tumor cells, allowing them to evade immune surveillance." (PMID 38280005, 2024). "This can be rationalised in the knowledge that c-Myc has a key tumour-specific role in regulating immune suppression by upregulating immune checkpoint proteins PD-L1 and CD47." (PMID 38521952, 2024). "An important approach in re-educating TAMs with anti-tumor properties using mAbs is to manipulate the CD47-SIRPα axis." (PMID 39169402, 2024). "By blocking CD47-induced inhibitory "don't-eat-me" signaling, ES004-B5 exerts superior antitumor activity in combination with anti-tumor-associated antigen antibodies in vitro and in vivo." (PMID 39257438, 2024). "The impact of the CD4+ T cells on tumor vascular normalization in the anti-CD47 Ab treatment was analyzed using IF double staining of CD31, α-SMA, and NG2." (PMID 38398223, 2024).
tumor (continued). "While dual targeting of CD47 and PD‐L1 has been shown to control tumor growth, the breadth of intratumoral CD8+ T cell responses resulting from this treatment has not been characterised." (PMID 39584189, 2024). "We found that the patient response rate was strongly correlated with the level of CD36 and CD47 expression on the surface of tumor cells." (PMID 39627379, 2024). "Experimentally, wild-type (WT) mice, antibiotic-fed mice and germ-free (GF) mice from different institutions differed in their immune anti-tumor effects against CD47." (PMID 38564002, 2024). "Monoclonal antibodies antagonizing the interaction of CD47 with its receptor SIRPα can eliminate tumor cells in vitro and in vivo and have shown therapeutic potential in several cancers." (PMID 38773982, 2024). "Elevated expression levels of CD47, CD68, and CD163 are commonly associated with a more immunosuppressive tumor microenvironment, which promotes tumor growth, metastasis, and resistance to treatment." (PMID 39682556, 2024). "This suggests that the benefit of SGRP-mediated CD47 blockade combined with CAR-mediated tumor killing relies on CAR target priming, leading to CAR T cell activation and persistence and enhanced myeloid cell infiltration to the brain." (PMID 39521782, 2024). "This team also designed a non-pathogenic strain of E. coli that specifically lyses within tumors and releases CD47 monoclonal antibodies, enhancing the activation of tumor-infiltrating T cells and improving the survival of tumor-bearing mice." (PMID 39135638, 2024). "Recently, CD47 blockade (Hu5F9-G4 or magrolimab), which is a macrophage checkpoint inhibitor that induces macrophage-mediated tumor killing, combined with rituximab showed potential efficacy in patients with relapsed or refractory FL." (PMID 39456838, 2024). "CD47 expression on tumor cells allows them to overcome intrinsic prophagocytic signals, and thereby escape phagocytosis." (PMID 38448430, 2024). "Upregulation of CD47 by tumor cells in order to avoid immune recognition and elimination is thus regarded as one of the critical steps during carcinogenesis." (PMID 39742254, 2024). "OMV-CD47nb, a bidirectional adapter, can simultaneously interact with CD47 on tumour cells and Toll-like receptors (TLRs) on TAMs and block “do not eat me” signalling on tumour cells while polarising TAMs to the M1 phenotype." (PMID 38561367, 2024). "Tumor macrophage infiltration was significantly higher in patients with CD47-positive expression than in patients with CD47-negative expression (P < 0.05)." (PMID 39652550, 2024). "There is mounting evidence that tumor cells increase the expression of CD47 to evade detection by the innate immune system." (PMID 38532108, 2024). "Subsequently, patient-derived cell (PDC) models and humanized patient-derived xenograft (Hu-PDX) models were utilized to evaluate the therapeutic efficacy of anti-CD47 immunotherapy in suppressing tumor growth." (PMID 38532108, 2024). "DIABLO (permutation test, p < 0.005) identified 15 transcripts in the CD20+ tumor cells (AOIs) to be positively associated with T-cell-rich MCLs, including IL7R, CD47, CD80, CD84 and NLRC5." (PMID 39001353, 2024). "In our previous studies, it has been demonstrated that nanoparticles carrying siCD47 can downregulate CD47 expression on the surface of tumor cells." (PMID 39697556, 2024). "The positive expression rate of CD47 in tumor tissues was significantly higher than that in adjacent non-cancerous tissues, with the difference being statistically significant (P< 0.05)." (PMID 39652550, 2024). "Enhanced tumor inhibition by the combination of Vtn-knockdown and anti-CD47 antibody treatment correlated with an increase in the infiltration of macrophages to the tumor microenvironment relative to no treatment or either treatment alone." (PMID 38773982, 2024). "CD47 was also considered as a tumor phagocytosis checkpoint marker and various cancers utilize it as an immune evasion tool." (PMID 39627379, 2024).
tumor (continued). "Meanwhile, TUG1 interacted with YBX1 to facilitate the upregulation of PD‐L1 and CD47 transcriptionally, which ultimately regulated tumor immune evasion." (PMID 38981064, 2024). "Reprogramming of tumor-associated macrophages (TAMs) to a M1 macrophage via targeting TAMs or tumor cells by engineered M1-derived EVs decorating IL-4 receptor or CD47 via postinsertion of targeting peptide increased anti-tumor immunity." (PMID 38660297, 2024). "In our study of NSCLC specimens, we assessed CD47 expression on tumor-infiltrating T lymphocytes using flow cytometry in tumor and adjacent normal tissues from 50 patients." (PMID 39652550, 2024). "Based on the mechanisms by which tumor cells evade macrophage phagocytosis as a result of their high expression of CD47 44, we engineered Exos to transmit a “don't eat me” signal to achieve targeted transport to hepatocytes." (PMID 38164154, 2024). "The stimulation of TSP-1 simultaneously targets both CD36 and CD47 harnessing the full anti-tumor activity of TSP-1." (PMID 38218979, 2024). "This unique affinity profile allows preferential binding to PD-L1 of tumor cells, suppressing the CD47 signaling pathway." (PMID 38475778, 2024). "Elevated CD47 expression on some cancer cells thereby serves as an innate immune checkpoint that limits phagocytic clearance of tumor cells by macrophages and antigen presentation to T cells." (PMID 38495618, 2024). "Analysis of The Cancer Genome Atlas datasets identified IFT57 as a top coexpressed gene with CD47 among 1156 human cancer cell lines and in most tumor types." (PMID 39201643, 2024). "CD47 is a protein that is overexpressed on multiple tumor cells, inhibiting the phagocytic function of DCs by binding to SIRPα." (PMID 39334927, 2024). "Blocking the CD47 “don’t eat me”-signal on tumor cells with monoclonal antibodies or fusion proteins has shown limited clinical activity in hematologic malignancies and solid tumors thus far." (PMID 38720892, 2024). "Significant growth delay was observed in the tumor growth for both the anti-CD47 Ab group and the anti-CTLA4 Ab group compared to the control group." (PMID 38398223, 2024). "Combination therapy of anti-CD47 antibodies with EGFR inhibitors demonstrates more effective inhibition of tumor growth." (PMID 39223632, 2024). "Monoclonal antibodies and fusion proteins blocking CD47/SIRPα signaling have demonstrated potent anti-tumor action in preclinical models and clinical studies." (PMID 39040441, 2024). "There is often mutual regulation among immune checkpoints in the TIME, which prompted us to further evaluate the PD-1, PD-L1, and CTLA4 protein levels in the tumor tissues using IHC after anti-CD47 Ab treatment." (PMID 38398223, 2024). "To the best of our knowledge, we are the first to compare the differences between CD47 abundance at different tumor grades in STS." (PMID 38493445, 2024). "mairei (AETC) promotes ubiquitination and degradation of CD47 in tumor cells, activating immune cells and enhancing the efficacy of PD-1 antibodies." (PMID 39223632, 2024). "In breast cancer models, anti-CD47 monoclonal antibodies combined with targeting-STING therapy promoted macrophage phagocytosis of tumour cells and CD8+ T-cell priming." (PMID 38303024, 2024). "Overexpression of CD47 enables tumor cells to evade immune surveillance via the blockade of phagocytic mechanisms and is associated with poor survival in various cancer." (PMID 39318624, 2024). "Univariate analyses showed that age, tumor type, MGMT unmethylation, CD47, and high TIGIT expression were all associated with OS, whereas gender, tumor location, and pTERT mutations were unrelated to OS." (PMID 38404571, 2024). "Here, we describe the immune landscape generated upon CD47 × PD‐L1 BisAb treatment within the tumor microenvironment and circulation." (PMID 39584189, 2024).